AHR (aryl hydrocarbon receptor)
Diseases named in the same sentence as AHR in open-access papers (continued):
Sharing a sentence is not in itself a finding about the gene and the disease.
melanoma (continued). "To investigate the molecular consequences of BRAFi-recruitment on AhR, we established the transcriptomes of BRAF-V600E melanoma cells (501Mel) exposed to Vem and to TCDD." (PMID 30429474, 2018). "More recently it was found that benzo[a]pyrene that is known to activate AHR and induce CYP1A1 represses melanogenesis in B16F10 mouse melanoma cells." (PMID 29632489, 2018). "Interestingly, depletion of basal Aldh1a1 levels in AhR-expressing melanoma cells did not significantly affect tumor growth, suggesting that the overactivation of Aldh1a1 is likely a causal factor increasing the tumorigenicity of AhR deficient melanoma cells." (PMID 26242870, 2015). "Loss-of-function studies validate this mechanism: L. reuteri ΔAAT (a Trp catabolism-deficient strain) fails to produce I3A or suppress melanoma growth, while CD8+ T cell-specific AhR knockout completely abrogates I3A-driven tumor suppression." (PMID 41181090, 2025). "In a preclinical study of melanoma, IDO inhibition in IDO-expressing B16 melanoma, but not wild-type melanoma, decreased the tumor size, while direct AhR inhibition decreased the tumor size in both IDO- and TDO-expressing tumors." (PMID 38339226, 2024). "Of note, the AHR/SRC axis has recently been discovered as a new therapeutic vulnerability that triggers resistance to BRAF (B-Raf proto-oncogene, serine/threonine kinase) inhibitors in melanoma." (PMID 37696456, 2023). "Together these results identify the central role of the AhR/SRC axis in supporting nongenetic cell reprogramming of melanoma cells exposed to targeted therapy." (PMID 36305167, 2022). "We performed co‐immunoprecipitation experiments to determine whether AhR and SRC are present in the same protein complex in melanoma cells (SKMel28)." (PMID 36305167, 2022). "In these low-AhR melanoma cells, KD87 led to an acivation of the AhR translocation." (PMID 35169210, 2022). "Interestingly, metformin treatment inhibits AhR signaling and VISTA expression in vitro and in melanoma mouse models." (PMID 36713558, 2022). "Overall, these results suggest that MAPKinase activation may co-occur with AhR-dependency and that elevated AhR levels may serve as a biomarker of sensitivity to MEK inhibitors in the context of NRAS-mutant melanoma." (PMID 33451095, 2021). "In addition to the Kyn-dependent pathway, AhR activation by FICZ (6-formylindolo [3,2-b]carbazole), a skin tryptophan photoproduct, was shown to promote TNFα-dependent inflammation and induce melanoma cell differentiation and the development of metastasis." (PMID 33451095, 2021). "BRAFi also act as non-canonical ligands for the transcription factor aryl hydrocarbon receptor (AhR) to maintain melanoma cells in a proliferative and drug sensitive state." (PMID 32466585, 2020). "The role of AhR in melanomagenesis is not clear, however, previous studies revealed involvement of this receptor in melanoma cell dedifferentiation and metastases in response to inflammation." (PMID 33114713, 2020). "Interestingly, IFN-γ treatment-induced dormancy in B16 melanoma cells in an IDO- and AHR-dependent manner." (PMID 31795255, 2019). "Finally, as BRAF somatic mutations characterize other human malignancies including colon cancer and melanoma, future research should clarify if the BRAF-mediated AHR activation is peculiar of PTC or a more general mechanism." (PMID 26392334, 2015). "Regarding AhR, its repression favours the growth of human hematopoietic stem cells, the development of mouse embryonic stem cells, the acquisition of an EMT phenotype in epithelial cells and the expansion of stem-like cells in melanoma." (PMID 26242870, 2015). "Depletion of aldehyde dehydrogenase 1a1 (Aldh1a1) impairs the pro-tumorigenic and pro-metastatic advantage of melanoma cells lacking AhR expression (sh-AhR)." (PMID 26242870, 2015). "Similarly, the expression of AhR was found to inhibit primary tumorigenesis, migration, and invasion in B16F10 melanoma cells when injected into AhR+/+ but not AhR−/− mice." (PMID 37106727, 2023).
melanoma (continued). "In addition, we show in melanoma cells that canonical activation of AhR mediates the activation of the SRC pathway and promotes the acquisition of an invasive and aggressive resistant phenotype to front‐line BRAFi treatment in melanoma." (PMID 36305167, 2022). "The direct role of AhR in regulating the phosphorylation of SRC (Y416) and EGFR (Y845) may promote together the acquisition of the aggressive/invasive EMT like phenotype of BRAFi‐resistant melanoma (Synopsis)." (PMID 36305167, 2022). "Thus, we tested ABT-263, SB505124, Afatinib, and CHIR−99021_1241 on the melanoma line SKMel28 in the presence, or not, of the AhR transcription factor (CRISPR-Cas9 silencing)." (PMID 33451095, 2021). "However, L-KYN 1 mM, KYNA 5 mM and FICZ 50 μM did not affect the gene expression of AHR in melanoma A375 and RPMI7951 cells." (PMID 33114713, 2020). "Moreover, Sox2 failed to rescue the migration of Aldh1a1-depleted sh-AhR + sh-Aldh1a1 cells, further supporting a functional interaction between Aldh1a1 and Sox2 in murine melanoma cells." (PMID 26242870, 2015). "In this context, the inverse correlation observed between AhR and Aldh1a1 could gain additional interest considering that AhR protein levels were reduced in high grade human melanomas as compared to non-malignant nevi." (PMID 26242870, 2015). "We have previously reported that stable AhR knockdown increased the tumorigenic and metastatic abilities of B16F10 melanoma cells, suggesting that this receptor could have a tumor suppressor role in melanoma." (PMID 26242870, 2015). "Thus, while A771726 is also able to inhibit A375 melanoma cells, these effects are independent of the AhR expression." (PMID 22815870, 2012). "Interestingly, the pro-tumoral phenotype caused by AhR depletion in the tumor cell required AhR expression in the microenvironment as AhR−/− mice could not support tumor growth and metastatization of melanoma cells interfered for AhR." (PMID 26242870, 2015). "This apparent correlation between Sox2 and Aldh1a1 was supported by the observation that ectopic Sox2 expression increased Aldh1a1 mRNA levels in sh-AhR but not in Aldh1a1-interfered melanoma cells, indicating that Sox2 could play a role in maintaining Aldh1a1 expression." (PMID 26242870, 2015). "Interestingly, Sox2 increased Aldh1a1 expression in sh-AhR but not in sh-AhR + sh-Aldh1a1 cells, suggesting that Aldh1a1 and Sox2 may be co-regulated in melanoma cells." (PMID 26242870, 2015). "IDO1, expressed by both LCs and melanoma cells, lead to the production of KYN, which directly stimulate LCs to express more IDO1 trough AhR without inducing CD83 expression." (PMID 35408802, 2022). "Our results show that, in SK-Mel-28 melanoma cells, dex up-regulated TDO and its downstream effector aryl hydrocarbon receptor (AHR) but not IDO1." (PMID 33806305, 2021). "Unexpectedly, we revealed that in drug-sensitive melanoma cells, BRAFi, in addition to inactivated oncogenic BRAF activity, functions as a non-canonical ligand of AhR." (PMID 30429474, 2018). "Although the decrease of AhR protein level was also previously reported in human melanoma A375 and RPMI-7951 cells exposed to KYN, this tryptophan metabolite did not affect gene expression of AHR in melanoma cell lines." (PMID 37245164, 2023). "However, the relation between AhR and SRC has not yet been explored in melanoma." (PMID 36305167, 2022).
asthma (82 papers, 2005 to 2026). "By using our asthma mouse model with AhR deficient (AhR-/-) mice, we found that cockroach allergen-induced increased airway inflammation and mucus production (AB-PAS) were enhanced in AhR-/- mice compared with WT mice." (PMID 34868022, 2021). "Recently, AhR has been associated with asthma and shown to mediate environmental pollutant-enhanced allergic lung inflammation, ROS-dependent degranulation and activation of mast cells." (PMID 34868022, 2021). "Aside from contributing to airway inflammation, we also demonstrated that loss of LXR activity reduced excessive mucus production and AHR, cardinal features of asthma." (PMID 27621817, 2016). "The aryl hydrocarbon receptor (AhR) is implicated in many diseases that are driven by immune/inflammatory processes, including major depressive disorder, multiple sclerosis, rheumatoid arthritis, asthma, and allergic responses." (PMID 38424040, 2024). "While evidence has shown that Muc5ac overexpression leads to the development of airway mucus plugging, AHR, and asthma exacerbations, the mechanisms underlying development and immune regulation of mucus production in response to allergens are not fully unveiled." (PMID 34868022, 2021). "On the other hand, AhR activation by particle-associated polycyclic aromatic hydrocarbons from the environment is pro-inflammatory, inducing mucus hypersecretion, airway remodelling, dysregulation of antigen presenting cells and exacerbates asthma features." (PMID 33233810, 2020). "AHR has been implicated in many diseases that are driven by immune/inflammatory processes, including major depressive disorder, multiple sclerosis, rheumatoid arthritis, asthma, and allergic responses, among others." (PMID 30513921, 2018). "Importantly, we made novel findings that BaP-activated AhR can bind to the promoter region of RhoA and regulate RhoA/Rho-kinase activation, and inhibition of RhoA significantly suppresses co-exposure-induced AHR, Th2-associated airway inflammation, and TGFβ1 signaling in a mouse model of asthma." (PMID 33936062, 2021). "In asthma, reduced vitamin D levels are associated with impaired lung function, increased AHR, and reduced GC response, suggesting that supplementation of vitamin D levels in patients with asthma may improve a number 0f parameters of asthma severity and treatment response." (PMID 33608061, 2021). "However, a role for the AhR in suppressing asthma caused by other environmental triggers, particularly those that are associated with neutrophilic asthma, remains unknown." (PMID 34744763, 2021). "This is consistent with previous work showing that elevated TSLP in lungs correlates with increased AHR in both mouse models and human asthma, and that neutralizing TSLP or downstream cytokines like IL-4 and IL-13 mitigates AHR and airway inflammation." (PMID 41259396, 2025). "AhR is a ligand-activated transcription factor that has been shown to play an important role in asthma control." (PMID 39681318, 2025). "Benzo[a]pyrene (BAP) activates AhR in the airways, promoting ROS production, upregulating mucin expression, and exacerbating airway inflammation and barrier dysfunction in asthma." (PMID 40559961, 2025). "On the other hand, AhR activation by PAHs is pro-inflammatory, inducing mucus hypersecretion, airway remodeling, dysregulation of antigen cells and exacerbating asthma features." (PMID 39681318, 2025). "The AhR pathway is complex, as it is potently expressed in the most immune cells involved in the pathophysiology of asthma." (PMID 38731707, 2024). "As a recognized receptor for environmental pollutants, activation of the AhR plays an important role in regulating the expression of specific proinflammatory genes and mediating the differentiation of Th2 cells in asthma." (PMID 39707175, 2024). "It has been previously shown that AHR in murine asthma models is increased by additional stimulation with IL-17A." (PMID 37443808, 2023).
asthma (continued). "Since AhR contributed to MnBP‐induced asthma exacerbation, we investigated the effect of an AhR antagonist on our MnBP‐treated allergic asthma model." (PMID 37315181, 2023). "As a receptor for EDCs and present on key immune cells in asthma, AhR is of great interest in MnBP‐induced asthma." (PMID 37315181, 2023). "Although not using EDCs, recent studies using other pollutants such as PM2.5 or diesel exhaust particles showed that airway inflammation in asthma aggravated through AhR mediation." (PMID 37315181, 2023). "Taken together, our findings indicate that the ACC1-FABP-PPARγ axis drives the proglycolytic metabolic reprogramming in ACC1-deficient iNKT cells, thereby downregulating iNKT-cell homeostasis, and functions, including iNKT cell-mediated AHR in asthma models." (PMID 37917548, 2023). "The present increase of mast cells in the airways is in accordance with a higher level of mast cells in the smooth layer of lung tissue in humans with asthma, which as such correlates to an increase of AHR." (PMID 36761882, 2023). "The researchers found that DEP-induced IL-25, IL-33, and TSLP expression was increased in primary bronchial epithelial cells from patients with mild asthma through the aryl hydrocarbon receptor and increased levels of acetyl-histone H3." (PMID 36674744, 2023). "When the Cd4-Cre::Acc1fl/fl and Acc1fl/fl control mice were induced to undergo OVA-mediated asthma, we indeed observed that the loss of ACC1 expression attenuated AHR and the total immune-cell numbers in the lung and the bronchoalveolar lavage fluid (BALF)." (PMID 37917548, 2023). "Herein, a mouse asthma model was induced using nebulized OVA to investigate the effect of CAVO on AHR." (PMID 39282108, 2023). "Exposure to particulate matter also activates AhR, and this activation is known to induce neutrophil inflammation in a mouse model of asthma." (PMID 37315181, 2023). "AhR activation can influence the inflammatory phase in both asthma and chronic obstructive pulmonary disease through inflammatory and resident cells in the lungs." (PMID 35743162, 2022). "The role of AhR in AT2 cells in airway inflammation was investigated in a mouse model of asthma with AhR conditional knockout mice in AT2 cells (Sftpc-Cre;AhRf/f)." (PMID 35935956, 2022). "Exposure to air pollution, especially particulate matter less than 2.5μm that easily reaches small airways and alveoli, via interacting aryl hydrocarbon receptor, promotes Th17 cell differentiation to aggravate asthma." (PMID 36032162, 2022). "In murine models of asthma, IL-9 has shown a role in driving AHR, airway remodeling, mast cell survival, and mucous cell metaplasia." (PMID 36032162, 2022). "Conversely, AhR activation is known to reduce airway inflammation in rodent models of asthma by modulating the production and secretion of Th2 cytokines such as interleukin (IL) 4, IL-5, and IL-15." (PMID 35743162, 2022). "We have found that expression of AhR was significantly increased in the airways of asthmatic patients and the mouse model of asthma." (PMID 35935956, 2022). "The relation between AhR function and airway inflammation in the initial phase is important not only in chronic obstructive pulmonary disease but also in asthma." (PMID 35743162, 2022). "Further studies suggest that active AhR signaling in MSCs regulates MSC suppressive activity by polarizing macrophages into anti-inflammatory M2 in asthma." (PMID 35935956, 2022). "As expected from previous work using the OVA-induced asthma model, AHR expression in response to increasing doses of methacholine increased in WT OVA/OVA mice compared to WT sham mice." (PMID 36457999, 2022). "Future studies should be addressed to understand the link between MSC and AhR during immunomodulation activity in asthma." (PMID 33959015, 2021).
asthma (continued). "Gut microbes are the major participants in tryptophan metabolism, which protects the host from developing asthma through indoleamine 2,3-dioxygenase-1 pathway and aryl hydrocarbon receptor activation." (PMID 34612663, 2021). "Using AhR-deficient (Ahr−/−) mice, we compared the function of the AhR in the response to ovalbumin (OVA; allergic asthma) vs. chlorine (Cl2; irritant-induced asthma) exposure." (PMID 34744763, 2021). "Cockroach allergen-induced Muc5ac expression and aryl hydrocarbon receptor (AhR) signaling activation was examined in the human bronchial epithelial cells (HBECs) and mouse model of asthma." (PMID 34868022, 2021). "As OVA is a well-characterized allergic asthma model, we utilized this model to test the importance of AhR expression on the suppression of this asthma phenotype." (PMID 34744763, 2021). "Collectively, our studies identified a functional axis of AhR–RhoA that regulates the activation of TGFβ1/Smad3 signaling, thereby leading to the development of allergic airway inflammation and asthma." (PMID 33936062, 2021). "While a role of the AhR in controlling asthma related-outcomes has emerged, these studies utilized mouse models of eosinophilic allergic asthma." (PMID 34744763, 2021). "In the context of asthma, AhR activation by TCDD or benzo[a]pyrene (B[a]P) can be pro-inflammatory and induce MUC5AC expression, leading to mucus hypersecretion, airway remodeling, dysregulation of antigen-presenting cells, and exacerbation of asthma." (PMID 34744763, 2021). "Collectively, these results support a differential role for the AhR in regulating asthma outcomes in response to diverse etiological agents." (PMID 34744763, 2021). "AHR pathway is reportedly involved in the pathogenesis of certain inflammatory lung diseases such as asthma, COPD, and silicosis." (PMID 33066647, 2020). "Taken together, all these data underpins the complexity of the AhR pathway, which leads to both beneficial and deleterious outcomes in asthma." (PMID 33233810, 2020). "These outcomes are reviewed in the following sections, and show both beneficial and deleterious effects in the asthma response either by the use of gene silencing, knock out mice or AhR antagonists." (PMID 33233810, 2020). "In peripheral mononuclear cells from uncontrolled allergic asthmatics, AhR and IL-22 mRNA expression are increased compared with controlled asthma and healthy subjects, suggesting a relationship with asthma control." (PMID 33233810, 2020). "Multiple lines of evidence support a protective effect of tryptophan metabolism via the IDO pathway and aryl hydrocarbon receptor activation in asthma." (PMID 32155960, 2020). "In this review, we summarize our current knowledge about AhR and the cell programmes it controls related to asthma pathophysiology." (PMID 33233810, 2020). "AhR agonists inhibit hepatic inflammation and fibrosis, and activation of hepatic stellate cells; the AhR in combination with IRF4 is induced by activin A to inhibit asthma responses, and this is blocked by the AhR antagonist CH223191." (PMID 32932962, 2020). "The aryl hydrocarbon receptor (AhR) is a ligand-activated transcription factor that has emerged as an important player in asthma control." (PMID 33233810, 2020). "Recent studies have focused on the potential importance of the aryl hydrocarbon receptor (AhR) in linking the PM exposure and the development of asthma and allergic diseases." (PMID 32411804, 2020). "In an in vivo study conducted on female BALB/c mice, casticin reduced oxidative stress in the lungs of mice with asthma, alongside reduced activity by the aryl hydrocarbon receptor (AHR) and goblet cell hyperplasia." (PMID 32178324, 2020). "As an important player in asthma pathogenesis, airway epithelial cells are known to activate interferon and AhR signaling pathways following HDM challenges." (PMID 31089182, 2019).